MALAT1 (metastasis associated lung adenocarcinoma transcript 1)
Diseases named in the same sentence as MALAT1 in open-access papers (continued):
Sharing a sentence is not in itself a finding about the gene and the disease.
breast cancer (continued). "MALAT1 was reported to be an endogenous regulator of breast cancer progression by down-regulating miR-124 and activating the CDK4/E2F1 signaling pathway." (PMID 28439401, 2017). "MALAT-1 regulates metastasis in breast cancer by inducing EMT via activation of the phosphatidylinositide 3-kinase—protein kinase B (PI3K-AKT) pathway." (PMID 27608009, 2016). "We identified for the first time that MALAT1 expression was correlated with ER and its target genes in breast cancer, providing a new perspective in MALAT1 function." (PMID 27191888, 2016). "The data showed that CDK4 was inhibited at both mRNA and protein levels in breast cancer cells treated with MALAT1-siRNA compared with MALAT1-sc." (PMID 26918449, 2016). "To determine if MALAT1 regulates the expression of similar set of cell cycle genes in breast cancer cells as well, we performed RT-qPCR to quantify the mRNA levels of several of these genes in control and MALAT1-depleted M4 cells." (PMID 27250026, 2016). "Results showed estrogen-dependent recruitment of eNOS and ERs on the HOTAIR and MALAT1 promoter region at the eNOS peaks in endothelial, breast cancer cells, and PCa cells." (PMID 27922078, 2016). "It has recently been reported that treatment of ER-negative basal-like breast cancer cell lines with high concentration of 17b-Estradiol (E2) decreased the cellular levels of MALAT1, with a concomitant decrease in cell proliferation, migration and invasion." (PMID 27250026, 2016). "The data suggested that MALAT1 was involved in cell proliferation through the CDK4/E2F1 signaling pathway in breast cancer." (PMID 26918449, 2016). "However, the mechanisms underlying the role of MALAT1 in breast cancer remain unclear." (PMID 26918449, 2016). "We also found that MALAT1 and miR-124 expression were decreased in breast cancer cells treated with siAGO (RNA- induced silencing complex, RISC, core family number protein)." (PMID 26918449, 2016). "The results showed that MALAT1 overexpression accelerated breast cancer cells proliferation, whereas CDK4-siRNA inhibited cancer cell proliferation." (PMID 26918449, 2016). "We sought links between MALAT1 mRNA level status and standard clinico-pathological and biological factors in breast cancer." (PMID 27172249, 2016). "Preclinical studies have shown the therapeutic efficacy of ASOs targeting MALAT1 in the mouse MMTV–PyMT breast cancer model." (PMID 27998273, 2016). "A very recent study from the Spector laboratory also pointed out the involvement of MALAT1 in regulating the expression and pre-mRNA splicing of genes that are involved in differentiation and pro-tumorigenic pathways in breast cancer model system." (PMID 27250026, 2016). "In the present manuscript we investigated the potential involvement of MALAT1 in inducing tumor progression in different subtypes of breast cancers." (PMID 27250026, 2016). "Upon E2, a significant increase of HOTAIR and MALAT1 transcripts was observed in breast cancer, PCa and benign prostate hyperplasia (C17IM) cells." (PMID 27922078, 2016). "In conclusion, this study suggests that the lncRNA MALAT1 (as the well-known lncRNA HOTAIR) is involved in breast cancer." (PMID 27172249, 2016). "Several signaling pathways have been proposed to explain the oncogenesis of MALAT1 in breast cancer." (PMID 27191888, 2016). "A recent study showed that MALAT1 promotes breast cancer (miR-1), liver fibrosis and cervical cancer (miR-145) progression by acting as a ceRNA." (PMID 27564100, 2016). "In the present study, our results indicated that MALAT1 expression was up-regulated in multiple breast cancer cell lines compared with normal breast cell line, as well as in ER-positive breast cancer tissues compared with adjacent normal breast cancer tissues." (PMID 27191888, 2016). "In luminal breast cancer cells, a whole-genome analysis identified several mutations in SRSF1-binding region of MALAT1." (PMID 27250026, 2016).
breast cancer (continued). "Compared with normal breast tissue, MALAT1 expression was up-regulated significantly in primary breast cancer and lymph node metastasis." (PMID 27191888, 2016). "To obtain further insight into MALAT1 dysregulated pathways in breast cancer, we evaluated by qRT–PCR mRNA expression of a large number of selected genes in 20 low-Δsv-MALAT1-expressing and 20 high-Δsv-MALAT1-expressing breast tumours." (PMID 27172249, 2016). "Taken together, these data show that MALAT1 is positively associated with CDK4 and negatively associated with miR-124 in clinical breast cancer tissues, which increased CDK4 expression though miR-124 in breast cancer cells." (PMID 26918449, 2016). "We found two breast cancer-related lncRNAs, MALAT1 and XIST, were significantly and differentially co-expressed with mRNAs (ALG14, TOX4, and C12orf32) in tumor and normal breast tissue via trans-acting mechanism." (PMID 27597120, 2016). "Our data shows that MALAT1-siRNA inhibits cell proliferation and induces G0/G1 cell cycle arrest in breast cancer cells." (PMID 26918449, 2016). "In summary, our data showed that miR-124 inhibited cell proliferation by CDK4 and MALAT1 induced cell proliferation by decreasing miR-124 in breast cancer." (PMID 26918449, 2016). "Taken these together, we conclude that MALAT1 inverts the inhibitory effect of miR-124 on the tumor growth of breast cancer cells in vitro and in vivo." (PMID 26918449, 2016). "MALAT1-siRNA inhibited breast cancer cell proliferation and cell cycle progression in vitro and in vivo." (PMID 26918449, 2016). "Experiments utilizing serum starvation and anisomycin –induced apopotosis provide insights into the oncogenic potential of MALAT1 in the context of apoptosis of the breast cancer cells." (PMID 27250026, 2016). "In order to study the function of MALAT1 in an isogenic cell line background, we expanded our screening to a well characterized and widely reported isogenic breast cancer progression cell line series, including four cell lines named M1, M2, M3, and M4." (PMID 27250026, 2016). "Our results revealed a novel breast cancer regulation model that was comprised of the MALAT1-miR-124-CDK4/E2F1 pathway in breast cancer." (PMID 26918449, 2016). "As YAP protein regulates transcription of MALAT1 gene in liver cancer, we tested the possible positive correlation between YAP protein and Δsv-MALAT1 mRNA levels in breast cancer." (PMID 27172249, 2016). "Nevertheless, little is known about the mechanism through which MALAT1 exerts its oncogenic activity in breast cancer, as well as its interaction with other molecules." (PMID 27191888, 2016). "Further studies are necessary to elucidate the genetic (or epigenetic) mechanisms responsible for the observed underexpression of Δsv-MALAT1, in breast cancer." (PMID 27172249, 2016). "Tumors containing regions of papillary morphology are occasionally reported in the PyMT mouse breast cancer model, and a recent study has shown that knockout of a long non-coding RNA called Malat1 can result in cystic, fluid-filled tumors in the PyMT model." (PMID 27329840, 2016). "MALAT1 has been shown to be differentially expressed in multiple tumors, including breast cancer, prostate cancer, and lung cancer." (PMID 27597120, 2016). "The expression levels of MALAT1 in breast cancer were categorized as low or high expression at the cut-off value of the median." (PMID 27191888, 2016). "In 26 pairs of estrogen receptor (ER)-positive breast cancer samples, MALAT1 expression was significantly up-regulated compared with adjacent normal tissues (P = 0.012)." (PMID 27191888, 2016). "In this study, we focused on the lncRNA MALAT1 that has been shown dysregulated in various cancer types, but poorly studied in breast cancer." (PMID 27172249, 2016). "The aim of the current study is to explore the role of MALAT1 in breast cancer oncogenesis and its potential value as a prognostic biomarker." (PMID 27191888, 2016).
breast cancer (continued). "In this study, we found that MALAT1 suppressed miR-124 expression in breast cancer, which inverted the inhibitory effect of miR-124 on the tumor growth of breast cancer cells in vitro and in vivo." (PMID 26918449, 2016). "A recent study demonstrated that, down-regulation of MALAT1 mouse mammary carcinoma model resulted in slower tumor growth accompanied by significant differentiation into cystic tumors and a reduction in metastasis." (PMID 27191888, 2016). "Based on data obtained from various BC cell lines and patient samples, we observed elevated levels of MALAT1 in luminal subtype of breast cancers." (PMID 27250026, 2016). "human breast carcinoma samples exhibited the highest expression of KDM5B and MALAT1 in advanced stage (T3 and T4) cancer with associated poorer overall survival." (PMID 26917489, 2016). "MALAT-1 is also upregulated in other human cancers, such as breast cancer, prostate cancer, colorectal cancer, liver cancer, and uterine cancer." (PMID 26448942, 2015). "In the MMTV-PyMT breast cancer mouse model, Malat1 exerts oncogenic activity by enhancing cell proliferation and tumor metastasis, and serves as a potential target for treatment." (PMID 27999732, 2015). "Perturbation of Malat1 by RNA depletion induces differentiation of mammary tumors, increases cell adhesion and decreases metastasis." (PMID 27999732, 2015). "Treatment of breast cancer cells with high levels of estradiol reduces MALAT1 transcription, reducing proliferation, migration, and invasion." (PMID 25400658, 2014). "The expression of MALAT1 was up-regulated in many kinds of human cancers such as breast cancer, prostate cancer, colon cancer, liver cancer, and uterus cancer." (PMID 24330491, 2013). "According to the literature, MALAT1 is strongly overexpressed in a variety of tumor types, including hepatoblastomas, hepatocellular carcinomas, breast cancer, and endometrial stromal sarcomas." (PMID 23717670, 2013). "An international team, searching on thousands of novel non-coding transcripts of the breast cancer transcriptome, has been able to identify more than three hundred reads corresponding to MALAT1." (PMID 20805891, 2010). "MALAT1, a long non-coding RNA, is pivotal in the progression of breast cancer." (PMID 41622408, 2026). "Our bioinformatics analysis, leveraging publicly available gene expression datasets from the GEO database, further corroborates this notion, revealing that MALAT1 expression is consistently elevated in tamoxifen‐resistant breast cancer cell lines compared to their sensitive counterparts." (PMID 41031251, 2025). "This study aimed to explore the molecular pathways connecting the long non-coding RNAs (lncRNAs) HOTAIR, UCA1, and MALAT1 with breast cancer stem cell-related genes FOXC2, SNAIL, and ZEB, focusing on their involvement in transcriptional regulation, proliferation, and survival." (PMID 40781106, 2025). "Notably, MALAT1 is frequently upregulated in breast cancer, where it exerts oncogenic effects by acting as a competing endogenous RNA (ceRNA)." (PMID 41031251, 2025). "To gain mechanistic insight into the function of the PAK5-MALAT1-nuclear HER2 in breast cancer, we wondered whether MALAT1 regulated HER2 mRNA." (PMID 40258843, 2025). "MALAT1 has proven to be important for the promotion of the metastasis of various cancers, such as colorectal cancer and pancreatic cancer, whereas it has been shown to suppress metastasis in breast cancer and glioma." (PMID 41300301, 2025). "Additionally, curcumin has been reported to inhibit key signaling cascades, including Wnt/β‐catenin and PI3K/AKT, both of which are known to be activated by MALAT1 in breast cancer." (PMID 41031251, 2025). "MALAT1 has proven to be important for the promotion of metastasis of various cancers such as colorectal cancer and pancreatic cancer, whereas it has been shown to suppress metastasis in breast cancer and glioma." (PMID 40331955, 2025).
breast cancer (continued). "Additionally, MALAT1 has been shown to regulate breast cancer progression through modulation of the PI3K/AKT/mTOR signaling pathway, contributing to tumor progression." (PMID 40781106, 2025). "This suggests that NanoCurcumin may mitigate the upregulation of MALAT1, which has been widely observed in endocrine‐resistant breast cancer." (PMID 41031251, 2025). "According to several studies, this long non-coding could be essential in developing and metastasizing TNBC and HER2-positive BC because the presence of metastatic lymph nodes is correlated with MALAT1 expression in breast cancer patients." (PMID 40951838, 2025). "Perhaps the MALAT1–HuR axis plays a pivotal role in the regulation of EMT in breast cancer." (PMID 38254873, 2024). "The findings implied that the suppression of MALAT1 could potentially impede the infiltration and invasiveness of breast cancer cells." (PMID 39764614, 2024). "Notably, our study identifies the MALAT1-WTAP axis as a novel player in breast cancer progression and metastasis, highlighting its potential as a tumor biomarker." (PMID 38862471, 2024). "Additionally, MALAT1, a long non-coding RNA located in the nucleus, functions as a suppressor of tumors in cases of breast cancer." (PMID 39553554, 2024). "Indeed, these “hubs” included several lncRNAs well known for their role in breast cancer, e.g., MALAT1 at rank 17, SNHG29 at rank 2, SNHG16 at rank 19, GAS5 at rank 1, XIST at rank 11, NEAT1 at rank 23, NORAD and others." (PMID 38838009, 2024). "MALAT1, one of the best-characterized lncRNAs and one of the most highly expressed genes in humans, was revealed by multiple groups to be relevant to breast cancer as well as to coronary artery disease, specifically as viewed through the prism of its interface with vitamin-mediated pathways." (PMID 38475720, 2024). "According to these results, MALAT-1 could be a crucial biomarker for determining a breast cancer patient's prognosis." (PMID 38511067, 2024). "Furthermore, upregulation of MALAT1 in human breast cancer cells has been identified to result in the downregulation of miR‐146b‐5p expression, thereby promoting cell proliferation and invasion." (PMID 39347925, 2024). "Besides, PNPO positively correlated with MALAT1 in breast cancer cells, whereas MALAT1 was negatively correlated with miR-216b-5p, suggesting a ceRNAs regulatory mechanism." (PMID 38475720, 2024). "Whether Malat1 suppresses metastasis at other anatomic sites (in addition to the lung and bone) and in cancer types in addition to breast cancer and melanoma warrants further investigation." (PMID 38493144, 2024). "MALAT1 is a long non-coding RNA that is known to suppress breast cancer lung metastasis." (PMID 38493144, 2024). "In summary, these collective findings underscore the substantial role of MALAT1 in orchestrating EMT in breast cancer and imply that it might be used as an approach to reduce the spread of BC." (PMID 39323624, 2024). "Moreover, flow cytometry of breast cancer (BC) cells with MALAT1 knockout showed an increased number of cells in the G0/G1 phase, with a simultaneous decrease in the number of cells in the S phase." (PMID 38674413, 2024). "We then analyzed the expression of MALAT1 in pre-osteoclasts (including monocytes and macrophages) and mature osteoclasts of the non-osteoporotic individual, osteoporosis patients, osteosarcoma patients, and patients with breast cancer bone metastases." (PMID 38493144, 2024). "The function of MALAT1 in breast cancer cells is still a matter of debate." (PMID 38791553, 2024). "METTL3 mediates the overexpression of MALAT1 in adriamycin resistant breast cancer through m6A." (PMID 37901333, 2023). "MALAT1 mRNA expression provedalso significantly upregulated in breast cancer tissues." (PMID 37538803, 2023).
breast cancer (continued). "Interestingly, MALAT1 can be transcribed in both HIF1α- and HIF2α-dependent manners and stimulate tumor growth and migration by sponging off miR-3064-5p in breast cancer cells, though downstream functional targets of miR-3064-5p have not been identified." (PMID 37583933, 2023). "Moreover, the overexpression of MALAT1 in breast cancer stem cells (CSCs) influences the stem cell-like phenotypes by modulation of SOX2." (PMID 36726376, 2023). "This demonstrates that the integration of lncRNA to an mRNA signature could improve the prognosis value, as was also demonstrated for the combinatorial use of lncRNA MALAT1 and Oncotype Dx, for predicting the diagnosis of early-stage breast cancer." (PMID 37108589, 2023). "Interestingly, HIF2α, along with HIF-independent mechanisms, also establishes chromatin interactions at the MALAT1 promoter to regulate its transcription and subsequent metastasis in breast cancer cells." (PMID 37583933, 2023). "LncRNA MALAT1 KD by ASO represses breast cancer cell growth in vitro and in vivo." (PMID 37041291, 2023). "In addition, MALAT1 interacts with miR-1 to promote the spread of breast cancer, a process that is slug-dependent." (PMID 37245177, 2023). "In addition, MALAT1 bound and inactivated the pro-metastatic transcription factor TEAD, thereby preventing TEAD from associating with its coactivator YAP in breast cancer." (PMID 37355516, 2023). "Surprisingly, they found a 7.2-fold increase in metastatic foci and 31-fold increase in the percent of lung areas with metastatic lesions in Malat1-KO mice as compared to Malat1 WT mice, suggesting a role for Malat1 in suppressing breast cancer metastasis to the lung." (PMID 37370745, 2023). "However, it isinteresting to note that the serum levels of MALAT1 can also be a potentialdiagnostic oncomarker of breast cancer." (PMID 37538803, 2023). "First, these data support a model where MALAT1 may be involved in the recruitment of PRC2 to a subset of genes in breast cancer cells." (PMID 37367050, 2023). "Furthermore, the serumlevel of MALAT1 in breast cancer patients was significantly higher than inpatients having benign breast conditions (p < 0.001)." (PMID 37538803, 2023). "MALAT1 silencing suppressed the proliferationof HER2+ breast cancer cells." (PMID 37538803, 2023). "The exosomes secreted by breast cancer cells contain high expression levels of MALAT1, which can be transferred to surrounding breast cancer cells to silence the miR-1-3p in the cells and promote the metastasis of breast cancer cells and chemotherapy resistance." (PMID 37907984, 2023). "Also, study demonstrated that MALAT-1 affects the stem cell-like phenotypes in breast cancer cells through regulation of Sox-2." (PMID 36685962, 2022). "MALAT1 binds to miR-216b as a competing endogenous RNA to restore Pyridox(am)ine-5- phosphate Oxidase deficiency (PNPO) and promote cell proliferation, migration and invasion in breast cancer." (PMID 35359390, 2022). "Two molecules identified from the screen could reduce MALAT1 levels and branching morphogenesis in an organoid model of breast cancer." (PMID 36230680, 2022). "This lncRNA is regulated by hypoxia in several human cancers, but the main mechanism of action may vary between tumor types, as exemplified by the report showing that cytosolic functions of MALAT1 are more important in breast cancer, than in other tumors." (PMID 35626715, 2022). "In breast cancer, the lncRNA MALAT1 and miR-100 are indirectly interlinked through VEGFA." (PMID 35359390, 2022). "Additionally, a recent research uncovers that hypoxia triggers cancer-cell-specific chromatin-chromatin interactions between enhancer-like cis-regulatory elements present at the lncRNA MALAT1 locus, which facilitates transcription of MALAT1 in breast cancer." (PMID 35842651, 2022). "MALAT1 has been found to act both oncogenic and tumor suppressor in breast cancer." (PMID 36358625, 2022).